MXD3 (MAX dimerization protein 3)
Diseases named in the same sentence as MXD3 in open-access papers (continued):
Sharing a sentence is not in itself a finding about the gene and the disease.
cancer (continued). "After adjusting for potential confounding factors, MXD3 expression level emerged as a significant independent predictor of cancer-specific survival in LUSC patients (HR = 3.028, 95% CI: 1.245–7.361, ⁣∗p = 0.015)." (PMID 40406509, 2025). "Multivariate Cox regression analysis identified MXD3 expression level and lymph node involvement (N stage) as independent prognostic factors for cancer-specific survival in LUSC patients." (PMID 40406509, 2025). "Overall, the multivariate Cox regression analysis reaffirms the independent prognostic value of MXD3 expression level and N stage in predicting cancer-specific survival outcomes in LUSC patients." (PMID 40406509, 2025). "In brief, our first pancancer study of MXD3 confirmed the high expression of MXD3 in cancer tissues by TCGA and Oncomine." (PMID 34859046, 2021). "The cancers with better OS curves for MXD3 body hypermethylated expression were as follows: LGG (p < 0.001), LIHC (p = 0.048), KIRC (p < 0.001), LAML (p = 0.009), UVM (p < 0.001), BLCA (p = 0.008), CESC (p = 0.002), BRCA (p = 0.003), and ESCA (p = 0.002)." (PMID 34859046, 2021). "As a targeted therapeutic site, MXD3 enhances the killing of cancer cells and reduces the toxicity suffered by normal cells." (PMID 34859046, 2021). "Our results revealed that patients suffering from cancers with higher MXD3 expression had poor OS, DSS, DFI, and PFI." (PMID 34859046, 2021). "Based on TCGA and GEO data, our first pancancer study of MXD3 confirmed the high expression of MXD3 in cancer tissues." (PMID 34859046, 2021). "To clarify the clinical value of MXD3, we analyzed the classic indexes of each cancer, such as OS, DSS, DFI, and PFI." (PMID 34859046, 2021). "Our results revealed that MXD3 is closely related to the occurrence and development of various systemic diseases and cancers." (PMID 34584637, 2021). "Overall, MXD3 was positively correlated with the immune score in most cancers but negatively correlated with the stromal score." (PMID 34859046, 2021). "Based on available TCGA data, we find that the MXD3.E7 is expressed at higher levels in normal cells when compared to cancer cells." (PMID 30838212, 2019). "Our lab previously found MXD3 to be expressed in a variety of cancers using an online bioinformatics platform to query serial analysis of gene expression (SAGE) cancer datasets." (PMID 30838212, 2019). "First, we found that MXD3 message levels are significantly higher in cancers relative to their normal tissue counterparts, specifically in 13/18 (~72%) of the datasets examined." (PMID 30838212, 2019). "In our previous studies in other cancer cell lines, knockdown and overexpression of MXD3 leads to reduced cell numbers." (PMID 30838212, 2019). "Here we use these tools along with our own analyses to answer questions regarding MXD3's putative role in cancers through the analyses of currently available TCGA datasets." (PMID 30838212, 2019). "As a result, it is difficult to quantitatively answer how much MXD3 is overexpressed in cancers relative to normal tissue." (PMID 30838212, 2019). "In summary, we demonstrate that MXD3 has two splice forms likely resulting from APA that are differentially expressed in cancer and normal tissue." (PMID 30838212, 2019). "A query of MXD3 gene alteration frequencies using cBioPortal for Cancer Genomics reveals that the MXD3 gene is infrequently altered in cancer." (PMID 30838212, 2019). "We find that many cancers significantly expressed MXD3 more than two times relative to normal tissues." (PMID 30838212, 2019). "Datasets from TCGA have been invaluable for exploratory analyses within the context of cancers and our analysis has provided useful insights into MXD3 expression in cancer." (PMID 30838212, 2019). "On the other hand, MXD3.E6 mRNA is expressed at higher levels in cancer cells compared to normal cells." (PMID 30838212, 2019). "In this study we leveraged datasets from The Cancer Genome Atlas to examine MXD3 across several cancers." (PMID 30838212, 2019).
cancer (continued). "Notably, recent evidence suggests that dysregulation of the MYC/MAX/MXD network contributes to the progression of multiple cancers, highlighting MXD3 as a gene of interest for further investigation in the context of LUSC." (PMID 40406509, 2025). "Notably, MXD3 expression levels exhibited a profound impact on cancer-specific survival in LUSC patients, ⁣∗p < 0.001)." (PMID 40406509, 2025). "Furthermore, our study contributes to the growing body of evidence supporting MXD3 as a potential therapeutic target in cancer." (PMID 40406509, 2025). "Considering the high levels of MXD3 expression found in a variety of cancer types, we hypothesize that it may play a substantial role in the disease." (PMID 39287260, 2024). "Moreover, pan-cancer analysis discovered that MXD3 interacted with gene ancestry (GA) and exacerbated observed survival disparities." (PMID 36704352, 2022). "MXD3 was positively correlated with mismatch repair genes overall in various cancers." (PMID 34859046, 2021). "Altogether, our study strongly suggests that MXD3 is an immune-oncogenic molecule and could serve as a biomarker for cancer detection, prognosis, therapy design, and follow-up." (PMID 34584637, 2021). "We further explored the methylation status of the MXD3 gene body and gene promoter in cancer." (PMID 34859046, 2021). "Combining patient data from databases such as TCGA and GEO may elucidate the cancer landscape of MXD3 expression and eventually contribute to the precision treatment of cancer patients." (PMID 34859046, 2021). "Altogether, our study strongly suggests that MXD3 is an immune-oncogenic molecule and could serve as a biomarker for cancer detection, prognosis, therapeutic design, and follow-up." (PMID 34584637, 2021). "In this study, we explored the oncogenic role of MXD3 across TCGA pan-cancers." (PMID 34584637, 2021). "Therefore, we analyzed gene expression and alteration co-occurrence to identify functional partners of MXD3 in cancers." (PMID 34584637, 2021). "Furthermore, we evaluated the effect of MXD3 expression on chemotherapeutic responses in clinical cancer cohorts." (PMID 34584637, 2021). "Aberrant expression levels of MXD3 have been seen in numerous cancers." (PMID 34943942, 2021). "Except for USC, ACC, and ESCA, MXD3 in most cancers was closely related to ferroptosis." (PMID 34859046, 2021). "Collectively, our study suggests that MXD3 could serve as a biomarker for cancer detection, prognosis, therapy design, and follow-up." (PMID 34584637, 2021). "Interestingly, we found that MXD3 expression levels correlated well with expressions of immunosuppressive cells in almost all cancer types." (PMID 34584637, 2021). "The function of MXD3 and MXD3 methylation on cancer prognosis was validated: most patients with high MXD3 gene body hypermethylation had better survival, while MXD3 may play opposite roles in different tumors." (PMID 34859046, 2021). "Furthermore, the enrichment analyses in 33 types of cancer indicated that MXD3 can potentially impact the regulation of autophagy, the cytosolic DNA sensing pathway, the RIG-I-like receptor, the Toll-like receptor signaling pathway, and antigen processing and presentation." (PMID 34859046, 2021). "Similarly, in most of the cancers that had a significant relationship with MXD3 expression in dendritic cells, a type of antigen-presenting cell, the number of dendritic cells was negatively correlated with MXD3 expression." (PMID 34859046, 2021). "Moreover, we found that MXD3 is hypomethylated in various cancer types, except KIRP." (PMID 34584637, 2021). "Such upstream regulators may be important for the overexpression of MXD3 in human cancers." (PMID 30838212, 2019). "The outcome of TMB analysis indicated that MXD3 was correlated with TMB in STAD, LIHC, BRCA, and 12 other cancers." (PMID 34859046, 2021). "Thus, MXD3 could serve as an early biomarker for cancer detection and follow-up." (PMID 34584637, 2021).
cancer (continued). "To identify the pathways in which genes act in cancers, we performed GSEA and GO analysis of the MXD3 expression level, taking the intersection of the two analyses with more than five significant pathways." (PMID 34859046, 2021). "Additionally, we explore the potential therapeutic implications of targeting MXD3, given its role in the MYC pathway, which is known to be involved in cancer cell proliferation and survival." (PMID 40406509, 2025). "Additionally, we determined that MXD3 was correlated with MSI in STAD, HNSC, COAD, and six other cancers." (PMID 34859046, 2021). "Overall, MXD3 expression was negatively correlated with TMB in 15 cancers and MSI in 9 cancers." (PMID 34859046, 2021). "We explored the negative relationship between MXD3 and TMB and MSI in most types of cancer, indicating the poor prognosis of patients with high MXD3 expression." (PMID 34859046, 2021).
metabolic disease (2 papers, 2021). A congenital disorder (due to inherited enzyme abnormality) or acquired (due to failure of a metabolically important organ) disorder resulting from an abnormal metabolic process. "A gene and disease network interaction analysis revealed that MXD3 has various gene functional partners associated with metabolic diseases, cell proliferation, immune system, and hematological disorders." (PMID 34584637, 2021).
MXD3 also shares sentences with these, for which no sentence is quoted: breast carcinoma (2 papers); hepatocellular carcinoma (2); melanoma (2); anaplastic astrocytoma (1); anaplastic oligodendroglioma (1); astrocytoma (1); B-cell lymphoma (1); cerebellar tumors (1); cervical cancer (1); cervical squamous cell carcinoma (1); colon cancer (1); colorectal cancer (1); COVID-19 (1); dyslipidemia (1); endocervical adenocarcinoma (1); head and neck squamous cell carcinoma (1); hematological disorders (1); kidney cancer (1); liver diseases (1); liver fibrosis (1); Liver Steatosis (1); lung adenocarcinoma (1); Lung Squamous Cell Carcinoma (1); lymphoma (1); mesothelioma (1); metastatic melanoma (1); nephrolithiasis (1); oligodendroglioma (1); pancreatic adenocarcinoma (1); prostate adenocarcinoma (1).
A further 5 diseases each share a sentence with MXD3 in 1 paper.